MIR552 (microRNA 552)
Synonyms: hsa-mir-552; MIRN552
Gene: MicroRNA gene on chromosome 1 (34,669,599 to 34,669,694, reverse strand). Ensembl gene ENSG00000207941.
Gene Ontology:
Biological process: miRNA-mediated post-transcriptional gene silencing
Cellular component: RISC complex
Homologues: Orthologues: chimpanzee ptr-mir-552 (100% identical), macaque mml-mir-552 (92% identical).